PARP4 (poly(ADP-ribose) polymerase family member 4)
Description:
Mono-ADP-ribosyltransferase that mediates mono-ADP-ribosylation of target proteins. Component of the vault particle, which is a massive ribonucleoprotein complex that may play a role in cargo transport and signal transduction.
Synonyms: ARTD4; PH5P; PARP-4; VPARP; ADPRTL1; PARPL; VAULT3; p193; VWA5C
Tractability: Small molecule: a structure with a bound ligand is known; a high-quality ligand is known; it belongs to a druggable protein family. PROTAC: ubiquitination databases record sites on it; its protein half-life has been measured; a small molecule that binds it is known.
Target class: Enzyme; Transferase
Gene: Protein-coding gene on chromosome 13 (24,420,931 to 24,512,925, reverse strand). Ensembl gene ENSG00000102699.
Subcellular location: Cytoplasm; Nucleus; Cytoplasm, cytoskeleton, spindle
Subcellular location (Human Protein Atlas): Cytosol; Microtubules; Nucleoplasm; Mitotic spindle; Primary cilium
Pathways (Reactome):
Disease: Maturation of nucleoprotein
Metabolism: Nicotinate metabolism
Gene Ontology:
Molecular function: enzyme binding; NAD+ poly-ADP-ribosyltransferase activity; NAD+-protein mono-ADP-ribosyltransferase activity; protein binding; DNA binding; NAD+-protein-aspartate ADP-ribosyltransferase activity; NAD+-protein-glutamate ADP-ribosyltransferase activity
Biological process: inflammatory response; protein modification process; DNA damage response; DNA repair; protein transport; response to xenobiotic stimulus
Cellular component: cytoplasm; cytosol; extracellular exosome; membrane; mitotic spindle; nucleoplasm; nucleus; spindle microtubule; ribonucleoprotein complex; spindle
Genetic constraint (gnomAD): Loss-of-function variants: 65 observed, 101.62 expected, observed/expected ratio (o/e) 0.64, 90% interval 0.52 to 0.79. The upper end of that interval is the gene's LOEUF score, 0.79, which puts it in group 3 of 6, group 1 being the genes least tolerant of losing a copy. Missense variants: 1,308 observed, 1,405.4 expected, observed/expected ratio (o/e) 0.93, 90% interval 0.89 to 0.97. Synonymous variants: 466 observed, 514.6 expected, observed/expected ratio (o/e) 0.91, 90% interval 0.84 to 0.98.
Homologues: Orthologues: chimpanzee PARP4 (98% identical), macaque PARP4 (92% identical), rabbit PARP4 (67% identical), dog PARP4 (66% identical), guinea pig PARP4 (65% identical), mouse Parp4 (64% identical), rat Mphosph8 (64% identical), zebrafish parp4 (39% identical). Paralogues in human: ITIH3 (10% identical), ITIH4 (10% identical), ITIH2 (9% identical), ITIH6 (9% identical), ITIH1 (9% identical), VWA5A (8% identical), VWA5B1 (8% identical), ITIH5 (8% identical), VWA5B2 (7% identical), VWA3A (7% identical), VWA3B (7% identical).
Diseases named in the same sentence as PARP4 in open-access papers:
PARP4 is named in the same sentence as 29 diseases in open-access papers, as found by Europe PMC text mining. Sharing a sentence is not in itself a finding about the gene and the disease. The quoted sentences say what the papers report.
breast carcinoma (10 papers, 2013 to 2025). "PARP4 has also been proposed as a candidate cancer susceptibility gene in thyroid and breast cancers, suggesting PARP4’s involvement in other cancer types." (PMID 39034402, 2024). "Consistently, whole-exome sequencing in patients with primary thyroid and breast cancer shows that the PARP4 mutation frequency is significantly higher than that in control individuals." (PMID 36035988, 2022). "Previous study found that rare variants containing T1170I in the PARP4 gene were detected at significant high frequency in participants with primary thyroid and breast cancers while their frequencies were only 0.5% in controls." (PMID 34923986, 2021). "Recently, PARP4 has been found to be mutated in patients having thyroid and breast cancer (Das, Kundu, Laskar, Choudhury, & Ghosh, 2018)." (PMID 31294536, 2019). "Low PARP4 level was linked with poorer prognosis in breast cancer." (PMID 39885134, 2025). "In addition, germline mutations in PARP4 were identified as a possible susceptible gene of primary thyroid and breast cancer." (PMID 35927682, 2022). "PARP4 may function as a tumor suppression and be identified as a possible susceptibility gene of primary thyroid and breast cancer." (PMID 34923986, 2021). "Whereas functional analysis indicates that PARP4 knockout inhibits the proliferation and colony formation of breast cancer cells, thus further investigations are warranted to clarify the role of PARP4 in cancer." (PMID 36035988, 2022). "Furthermore, high expression of PARP4 has been reported in breast cancer with poor outcomes." (PMID 33811746, 2021). "Apart from KL and PARP4, the 13q linkage peak also includes known candidate genes for inflammation, e.g., arachidonate 5-lipoxygenase-activating protein (ALOX5AP), and cancer, e.g., breast cancer 2 early onset (BRCA2), all of which may be involved in the aging process." (PMID 24036517, 2013).
ovarian carcinoma (7 papers, 2021 to 2025). A malignant neoplasm originating from the surface ovarian epithelium. "The mechanism of action is based on differential methylation profiles between ovarian cancer cell lines at the PARP4 promoter, leading to the conclusion that this MART should be considered a diagnostic marker of great interest." (PMID 41463260, 2025). "Despite their suppressive role, PARP4 expression is also associated with resistance to cisplatin treatment, as evidenced by the restoration of sensitivity in resistant ovarian cancer cells following PARP4 silencing with small interfering RNA (siRNA)." (PMID 41463260, 2025). "Several reports link PARP4 overexpression with multidrug resistance genes such as MVP, and, in particular, it was shown by IHC methods that higher levels of PARP4 correlate with higher grade ovarian cancer." (PMID 33811746, 2021).
glioma (3 papers, 2022 to 2024). A benign or malignant brain and spinal cord tumor that arises from glial cells (astrocytes, oligodendrocytes, ependymal cells). "miR-125a-3p is considered as a tumor suppressor underlying the regulation of oncogenic circ-PARP4, which provides a novel and potential target for glioma therapy." (PMID 35883576, 2022). "Circ-PARP4 up-regulates glioma cell proliferation, migration, invasion, and epithelial-mesenchymal transformation." (PMID 35883576, 2022). "The results revealed a positive correlation between the expression of genes such as ZC3HAV1, TIPARP, PARP4, PARP14, and PARP15 and the abundance of various immune cell types in gliomas." (PMID 39724285, 2024). "In vivo and in vitro investigations indicated that circ-PARP4, as a miRNA sponge, directly interacted with miR-125a-5p, which then controlled FUT4 to produce the oncogenic influence on glioma behavior." (PMID 35883576, 2022).
lung carcinoma (3 papers, 2021 to 2025). "As PARP4 copy number loss was associated with EGFR and KRAS mutations, we selected two additional classic lung cancer cell lines bearing EGFR or KRAS mutations that had moderate basal PARP4 expression." (PMID 39034402, 2024). "In vitro and in vivo tumorigenicity assays were used to study the functional effects of PARP4 loss and mutation in multiple lung cancer cell lines." (PMID 39034402, 2024). "PARP4 depletion or mutation (I1039T) promotes the tumorigenicity of KRAS- or EGFR-driven lung cancer cells." (PMID 39034402, 2024). "This provided the first indication that hnRNPM and PARP4 likely promoted intron removal from certain genes in lung cancer, but the precise mechanism remains to be determined." (PMID 39034402, 2024). "Similarly, PARP4 KO models show increased tumorigenicity in lung cancer cells and higher proliferation in the HCC1143 cell line of breast ductal carcinoma, indicating a tumor-suppressive role for these MARTs." (PMID 41463260, 2025). "Examination of publicly available lung cancer gene expression datasets revealed that PARP4 expression levels were lower in lung cancer samples than in matched normal tissue; this underscored the observation that PARP4 expression is downregulated or lost during lung cancer progression." (PMID 39034402, 2024). "Taken together, these findings provide insights into how the loss of PARP4 function in LUAD could regulate splicing events, possibly through hnRNPM, thereby contributing to lung cancer pathogenesis." (PMID 39034402, 2024). "To identify PARP4-hnRNPM interaction site(s), we chose the HEK293T cell line which expresses hnRNPM but has low expression of PARP4 compared to the A549 and iSAEC-K lung cancer cells." (PMID 39034402, 2024). "POLQ, BRCA2, ATM, ATR, PARP4, and POLD1 alterations were most commonly observed in the entire advanced lung cancer cohort." (PMID 34604048, 2021). "However, the role of hnRNPM in the context of lung cancer and its regulation by PARP4 has not been clarified." (PMID 39034402, 2024).
thyroid cancer (3 papers, 2022 to 2025). "A study observed that two PARP4 mutations were found in 43% of breast and thyroid cancer patients." (PMID 39885134, 2025). "PARP4, another member of the PARP superfamily, has not been reported in samples of MPM, although it has been reported in breast or thyroid cancer." (PMID 39852534, 2025).
lung adenocarcinoma (2 papers, 2014 to 2024). A carcinoma that arises from the lung and is characterized by the presence of malignant glandular epithelial cells. "Leveraging on our whole-exome sequencing of the largest Asian lung adenocarcinoma (LUAD) cohort (n = 302), we now functionally assess the mechanistic role of a novel driver, PARP4." (PMID 39034402, 2024). "We identified several targetable pathways in EGFR/KRAS/ALK-negative lung adenocarcinoma including PI3K/mTOR signaling (TSC1, PIK3CA, AKT2), receptor tyrosine kinase signaling (ERBB4), cell cycle regulation (CHEK2, CDC27), and DNA repair (PARP4)." (PMID 24576404, 2014). "PARP4 is a novel modulator of lung adenocarcinoma, where its tumor suppressive activity is mediated not through the vault complex—unlike conventionally thought, but in association with its novel interaction partner hnRNPM, thus suggesting a role for splicing dysregulation in LUAD tumorigenesis." (PMID 39034402, 2024).
melanoma (2 papers, 2025). A malignant, usually aggressive tumor composed of atypical, neoplastic melanocytes. "PARP4 deficiency sensitizes melanoma cell lines to treatment with ATM inhibitors (ATMi), thus attributing to it an active role as an oncoprotein in melanoma." (PMID 41463260, 2025). "Moreover, inhibiting PARP4 could improve melanoma cell sensitivity to Ataxia telangiectasia mutated (ATM) inhibitors in vitro and in vivo." (PMID 39885134, 2025). "In conclusion, our findings provide novel insights into the functional role of PARP4 in DNA damage repair and melanoma pathogenesis." (PMID 39885134, 2025). "For example, it has been described that in melanoma, PARP4 migrates to the nucleus where it promotes proper DNA repair by the NHEJ system, modifying the Ku80 protein through MARylation." (PMID 41463260, 2025). "According to the Human Protein Atlas (HPA) database, immunohistochemical analysis revealed significantly higher levels of PARP4 protein in melanoma tissues (N = 24) compared to normal skin tissues (N = 5) (P < 0.001)." (PMID 39885134, 2025). "Immunofluorescence staining revealed that PARP4 was primarily localized in the cytoplasm, which was consistent with the immunohistochemical result in melanoma tissues based on the HPA database." (PMID 39885134, 2025). "Subsequently, a preclinical mice model was established to demonstrate that melanoma with low expression of PARP4 was more sensitive to KU55933 in vivo." (PMID 39885134, 2025). "Further analysis using the Cancer Genome Atlas (TCGA) database confirmed that PARP4 expression was notably higher in melanoma samples (N = 461) compared to normal skin samples (N = 558)." (PMID 39885134, 2025). "To further explore the role of PARP4 in melanoma, we examined the expression status of PARP4 in melanoma cell lines." (PMID 39885134, 2025). "The low expression of PARP4 is significantly associated with defective DSB repair markers and poor prognosis in melanoma." (PMID 39885134, 2025). "Our study demonstrated that melanoma with low PARP4 expression was more sensitive to KU55933 in vitro and in vivo." (PMID 39885134, 2025). "Importantly, PARP4 knockdown enhanced melanoma cell sensitivity to ATM inhibitors in vitro and in vivo, suggesting the potential of exploiting synthetic lethality as a therapeutic strategy." (PMID 39885134, 2025). "Further studies have shown that PARP4 could be a prognostic biomarker in melanoma patients and participate in DSB repair through the NHEJ pathway." (PMID 39885134, 2025). "Firstly, we investigated PARP4 expression within melanoma tissues." (PMID 39885134, 2025). "Targeted molecular inhibition in the HR repair pathway in PARP4-low expression melanoma could lead to synthetic lethality and therapeutic effects." (PMID 39885134, 2025). "Overall, our study provides new and valuable insights into the function of PARP4 and melanoma pathogenesis and suggests that ATM inhibitor may be a promising therapeutic approach for treating melanoma with low PARP4 expression." (PMID 39885134, 2025). "Moreover, our study also suggests that the ATM inhibitor may represent a potential therapeutic approach for treating melanoma with low PARP4 expression, offering a potential avenue for individualized treatment strategies." (PMID 39885134, 2025). "Our results have suggested that the knockdown of PARP4 could reduce the repair efficiency of the NHEJ pathway, prompting us to investigate whether melanoma cells with low PARP4 expression were more sensitive to DNA damage repair inhibitors based on the synthetic lethal strategy." (PMID 39885134, 2025). "Firstly, low PARP4 expression was significantly related to defective DSB repair, genome instability, and shorter DFS and OS in melanoma." (PMID 39885134, 2025). "PARP4 knockdown and overexpression significantly affected the IC50 value of KU55933 in FLFMM34 and A2058 melanoma cell lines, with cells with low PARP4 expression had more sensitivity towards KU55933." (PMID 39885134, 2025).
melanoma (continued). "Our study highlighted the crucial role of PARP4 in DNA damage repair and its impact on the sensitivity of ATM inhibitor in melanoma therapy." (PMID 39885134, 2025). "Further validation confirmed that PARP4 participated in DSB repair, and when PARP4 was knocked down, melanoma cells failed to manage the overwhelming DNA damage, leading to cell apoptosis and cell cycle G2/M arrest." (PMID 39885134, 2025). "Therefore, to explore the role of PARP4 in melanoma pathogenesis, we established siRNA and overexpression plasmid against PARP4 to secure the knockdown and overexpression of PARP4 in FLFMM34 and A2058 melanoma cells, respectively." (PMID 39885134, 2025). "Moreover, the data of cutaneous melanoma from TCGA database indicated that low PARP4 expression was significantly related to shorter disease-free survival (DFS) (P = 0.037) and overall survival (OS) (P = 0.023), indicating its significant role in the development and prognosis of melanoma." (PMID 39885134, 2025).
chronic hepatitis B (1 paper, 2020). "In a study of 48–52-year-old male hepatocellular carcinoma patients diagnosed with chronic hepatitis B, PARP4 variants were detected in > 10% of the whole-genome sequencing samples, with functional inhibitions of DNA BER and tumor cell apoptosis in vivo." (PMID 32316696, 2020).
colon tumors (1 paper, 2024). "When challenged with a chemical carcinogen, however, these PARP4-deficient mice were more prone to developing dimethylhydrazine-induced colon tumors." (PMID 39034402, 2024). "Prior to this study, PARP4 knockout mice were found to be more likely than wild-type mice to develop colon tumors when challenged with the chemical carcinogen dimethylhydrazine, underscoring its potential tumor suppressive role." (PMID 39034402, 2024).
colorectal NETs (1 paper, 2021). "The results of these exploratory analyses need to be confirmed, and functional experiments demonstrating the role PARP4 in CRC or in colorectal NETs need to be performed." (PMID 34976832, 2021). "However, similar to CRC or colorectal NETs, the role of PARP4 in OC has not been validated with strong experimental evidence." (PMID 34976832, 2021).
cutaneous melanoma (1 paper, 2025). A primary melanoma arising from atypical melanocytes in the skin. "Next, we found that low PARP4 expression was significantly correlated with high telomeric allelic imbalances (TAI) values and HRD_sum values in cutaneous melanoma according to the TCGA database." (PMID 39885134, 2025).
endometrial cancer (1 paper, 2022). Primary or metastatic malignant neoplasm involving the endometrium (mucous membrane that lines the endometrial cavity). "Further, we analyzed the enriched RNAs in apoptosis pathways, and the CPTAC database showed that their encoded proteins were upregulated in endometrial cancer tissues, including ITPR3, LMNB1, PARP1, PARP4, and TUBA1C." (PMID 36566215, 2022). "Then we analyzed the RNAs enriched in the apoptotic pathway through CPTAC database, and showed that the protein level of ITPR3, LMNB1, PARP1, PARP4, and TUBA1C were upregulated in endometrial cancer tissues." (PMID 36566215, 2022).
endometriosis (1 paper, 2017). The growth of functional endometrial tissue in anatomic sites outside the uterine body. "Results from gene-based meta-analysis identified class II major histocompatibility complex transactivator (CIITA) and poly(ADP-ribose) polymerase family member 4 (PARP4) as associated with endometriosis risk at exome-wide significance level." (PMID 28900119, 2017). "Our gene-based analyses of exome-array data identified CIITA and PARP4 as significantly associated with endometriosis susceptibility." (PMID 28900119, 2017). "PARP4 also showed exome-wide significant association with endometriosis risk in the SKAT test (P = 5.9 × 10−7)." (PMID 28900119, 2017).
esophageal squamous cell carcinoma (1 paper, 2021). Esophageal squamous cell carcinoma (ESCC) is a type of esophageal carcinoma (EC) that can affect any part of the esophagus, but is usually located in the upper or middle third. "Single‐cell intratumoral stemness analysis revealed that PARP4 is a cancer stemness-associated gene in esophageal squamous cell carcinoma (ESCC)." (PMID 34976832, 2021).
liver cancer (1 paper, 2016). An epithelial or non-epithelial malignant neoplasm that arises from the liver. "When we selected variants listed in the COSMIC database and labeled them as the same cancer type, most were common variants, while a missense variant in PARP4 of stomach cancer was a shared variant and CTNNB1 of liver cancer was a private variant." (PMID 27010638, 2016).
ovarian tumor (1 paper, 2024). "The role of genes encoding such proteins, LUC7L2, MRPL46, MRPL14, PARP4, STRAP, and PAPOLA, in ovarian tumor development has already been investigated in the literature." (PMID 39456618, 2024).
salivary gland carcinoma (1 paper, 2020). A carcinoma that arises from the major or minor salivary glands. "A genome-wide association study of 309 salivary gland carcinoma (SGC) patients and 535 controls without any carcinoma identified that common genetic variants in PARP4 were associated with SGC development." (PMID 32316696, 2020).